BUB1 (BUB1 mitotic checkpoint serine/threonine kinase)
Diseases named in the same sentence as BUB1 in open-access papers (continued):
Sharing a sentence is not in itself a finding about the gene and the disease.
colorectal cancer (18 papers, 2011 to 2023). "Mutations in BUB1 can cause mosaic variegated aneuploidy and increase the risk of colorectal cancer at a young age." (PMID 33597717, 2021). "Previously, mitotic checkpoint defects and the inactivation of the BUB1 gene have been implicated in human colorectal cancer cells." (PMID 29618387, 2018). "To date, only one study has found such mutations; BUB1 mutation is associated with lymph node metastasis and shorter relapse-free survival after surgery in colorectal cancers." (PMID 22022424, 2011). "Moreover, the mutation or haploinsufficiency of BUB1 or BUB3 led to an increased risk of colorectal cancer at a young age." (PMID 36787437, 2023). "Germline mutations in BUB1 and BUB3 have been reported to increase the risk of developing colorectal cancer (CRC) at young age, in presence of variegated aneuploidy and reminiscent dysmorphic traits of mosaic variegated aneuploidy syndrome." (PMID 29448935, 2018). "Germline mutations in BUB1 and BUB3 are associated with an increased risk of colorectal cancer." (PMID 32596342, 2020). "Furthermore, colorectal cancer patients showing Bub1 and Bub1b upregulation have a shorter relapse-free survival with respect to the groups showing normal expression of these genes." (PMID 26009897, 2015). "Abnormal expression of BUB1 and BUB1B were resulted in the prognosis of patients with brain tumor, glioblastoma, colorectal cancer, and NSCLC, and resulted in the impairment of mitotic checkpoint function." (PMID 33186389, 2020). "Remarkably, the levels of the Bub1 and BubR1 proteins of the SAC showed a significant and comparable decrease in both colorectal cancer cell lines upon Twist1 overexpression." (PMID 32337580, 2020).
prostate carcinoma (17 papers, 2018 to 2026). A carcinoma that arises from epithelial cells of the prostate gland. "BUB1 encodes a mitotic checkpoint Ser/Thr kinase that has recently been implicated as a key regulator of prostate cancer progression." (PMID 30616540, 2019). "For example, blocking BUB1 kinase activity can effectively reverse taxane resistance in castration-resistant prostate cancer." (PMID 40180891, 2025). "We showed that ectopic expression of MYB directly transactivates the BUB1 gene by binding to its promoter region, in line with what was recently observed by Cheng and colleagues in prostate cancer." (PMID 38112379, 2024). "Similar to circ_0004087 in function, the result of flow cytometry indicated that BUB1 boosted the DTX resistance in prostate cancer cells." (PMID 35659274, 2022). "Altogether, BUB1 is a potential tumor-promoting gene and partly renders prostate cancer cells the DTX resistance." (PMID 35659274, 2022). "Based on WGCNA module selecting and gene expression analysis, BUB1, KIF2C, CDC20, and PBK were eventually detected to be potentially associated with the clinical pathological features of prostate cancer." (PMID 35360870, 2022). "BUB1 is component of spindle checkpoint for proper chromosome segregation and its up-regulation was reported in human prostate cancer." (PMID 31681566, 2019). "Based on our cross‐species data, we would thus predict a compound such as OTS167, which is able to inhibit both MELK and BUB1, to be more effective in targeting prostate cancer cells than single inhibitors of either kinase." (PMID 29437778, 2018). "In addition, the circ_0004087/SND1/MYB/BUB1 axis was reported to modulate the error mitosis correction mechanism in prostate cancer cells." (PMID 36803376, 2023). "Also, the mechanism of BUB1 in regulating the development of prostate cancer remains to be explored." (PMID 35360870, 2022). "A recent study demonstrated that BUB1 mitotic checkpoint serine/threonine kinase B (BUB1B) could promote the proliferation of prostate cancer." (PMID 34298705, 2021). "In our study, the expression of BUB1 mRNA was significantly elevated in the central nervous system, bladder, cervical, brain, ovarian, breast, gastric, colorectal, esophageal, head, pancreatic, liver, neck, lung, and prostate cancers, as well as lymphomas and sarcomas." (PMID 36787437, 2023). "In prostate cancer cells, a decrease in its expression promotes the expression of proliferation-related genes MELK, NCAPG, BUB1, and CDK1, thereby promoting cell proliferation." (PMID 41546098, 2026). "However, experimental validation of BUB1 and KIF2C in prostate cancer was unavailable in the HPA database, which were valuable to be verified based on more experiments." (PMID 35360870, 2022). "Our previous studies revealed that tumor-suppressive miR-145-3p was closely involved in human cancer pathogenesis by targeting oncogenes, for example, MTDH in LUSQ; MELK, NCAPG, BUB1, and CDK1 in prostate cancer; MYO1B in head and neck cancer; and MYO1B and DHRS2 in esophageal cancer." (PMID 31514295, 2019).
liver cancer (15 papers, 2020 to 2024). An epithelial or non-epithelial malignant neoplasm that arises from the liver. "BUB1 is downregulated in sarcomas, lymphomas, and lung tumors, whereas BUB1 upregulation is associated with liver cancer." (PMID 34884561, 2021). "In addition, the significance of BUB1 in tumor cell proliferation was demonstrated in vitro and the molecular mechanism underlying BUB1 function in liver cancer growth was evaluated." (PMID 32269624, 2020). "Dysregulation of BUB1 has been described in a variety of tumours, including T-cell leukaemia, adenoid cystic carcinoma, bladder cancer, liver cancer, and breast cancer." (PMID 38396175, 2024). "In contrast, upregulation of BUB1 significantly promoted cell proliferation, while downregulation of BUB1 expression inhibited the proliferation of liver cancer cell lines." (PMID 38144520, 2023). "BUB1 expression is correlated with unfavorable prognosis in patients with malignant tumors, including breast and liver cancers." (PMID 35627287, 2022). "BUB1 expression is correlated with unfavorable prognosis in patients with breast cancer and liver cancer." (PMID 34884561, 2021). "At present, BUB1 is mostly studied in liver cancer, involving multiple signal transduction pathways." (PMID 34235075, 2021). "Increased BUB1 expression signally facilitates cell proliferation, while decreased BUB1 expression restrains liver cancer cells proliferation." (PMID 33767726, 2021). "Western blotting results revealed that the establishment of overexpression and knockdown of BUB1 in liver cancer cell lines was successful." (PMID 32269624, 2020). "It was observed that cell proliferation was significantly increased following BUB1 overexpression, whereas knockdown of BUB1 inhibited liver cancer cell proliferation." (PMID 32269624, 2020). "In summary, the present study demonstrated that BUB1 increased the proliferation of liver cancer cells." (PMID 32269624, 2020). "The present study demonstrated that BUB1 mRNA expression levels and the intensity of immunohistochemical staining were significantly increased in liver cancer tissues compared with normal tissues." (PMID 32269624, 2020). "Initially, reverse transcription-quantitative (RT-q)PCR and immunohistochemistry were used to determine the expression of BUB1 in liver cancer and adjacent normal tissues." (PMID 32269624, 2020). "Overexpression of BUB1 significantly promoted cell proliferation, whereas knockdown of BUB1 expression inhibited the proliferation of liver cancer cell lines." (PMID 32269624, 2020). "Several studies have demonstrated the unfavorable prognostic role of BUB1 in liver cancer based on bioinformatics analysis." (PMID 32269624, 2020). "The results of the present study demonstrated that BUB1 mRNA and protein expression levels were significantly increased in liver cancer tissues compared with normal tissues." (PMID 32269624, 2020). "The mRNA expression levels of BUB1 in 24 pairs of liver cancer tissues and the corresponding normal tissue were examined." (PMID 32269624, 2020). "Moreover, BUB1 promotes the proliferation and vertical migration ability of liver cancer cells by activating phosphorylation of SMAD2." (PMID 36787437, 2023). "Based on the clinical data, it was hypothesized that BUB1 may promote the proliferation of liver cancer cells." (PMID 32269624, 2020). "In addition, western blotting confirmed successful overexpression and knockdown of BUB1 in liver cancer cell lines." (PMID 32269624, 2020). "The present study demonstrated that BUB1 may promote liver cancer cell proliferation by activating the phosphorylation of SMAD2." (PMID 32269624, 2020). "The present study aimed to explore the biological function of BUB1 in liver cancer." (PMID 32269624, 2020). "In the present study, the importance of BUB1 in the progression of liver cancer was investigated." (PMID 32269624, 2020). "However, the molecular biological function of BUB1 in liver cancer still remains unclear." (PMID 32269624, 2020).
liver cancer (continued). "Therefore, BUB1 may promote proliferation of liver cancer cells by activating phosphorylation of SMAD2, and BUB1 may serve as a potential target in the diagnosis and/or treatment of liver cancer." (PMID 32269624, 2020).
glioblastoma (14 papers, 2011 to 2025). The most malignant astrocytic tumor (WHO grade IV). "Compared with normal control tissues, BUB1 expression is significantly up-regulated in glioblastoma multiforme samples." (PMID 38167011, 2024). "It has been found that numerous tumors, such as glioblastoma and gastric adenocarcinoma, harbor expression changes in BUB1, BUB1B, and TTK as well as checkpoint dysfunction." (PMID 32090084, 2020). "BUB1 inhibition has been reported to decrease proliferation and to improve efficiency of temozolomide and radiation treatment of glioblastoma cells." (PMID 32604718, 2020). "BUB1 (budding uninhibited by benzimidazoles 1) plays a key role in the proliferation and radioresistance of glioblastoma (GBM) in a FOXM1-dependent manner." (PMID 33644115, 2021). "In glioblastoma (GBM), BUB1 was highly expressed with elevated expression related to poor prognosis and radioresistance in GBM patients." (PMID 35859724, 2022). "We established that Msi1 levels affect the expression of Bub1, Bub1B, MADL1 and CDC20 and Bub3 is a direct target of Msi1 in glioblastoma cells." (PMID 33804958, 2021). "However, BUB1 and BUBR1 inhibition has been shown to enhance radiation sensitivity in pediatric glioblastoma cells." (PMID 24743044, 2014).
lung carcinoma (13 papers, 2009 to 2026). "Dysregulated BUB1 expression is implicated in various malignancies, including lung cancers." (PMID 39409911, 2024). "More importantly, it has been reported that hypoxia upregulated BUB1 to accelerate lung cancer development." (PMID 40914946, 2026). "It has been reported that upregulation of BUB1 was involved in hypoxia‐induced epithelial‐mesenchymal transition of lung cancer cells." (PMID 40914946, 2026). "Our findings suggest that BUB1 inhibitor sensitizes lung cancer cell lines to chemotherapy, radiotherapy, and chemoradiation and thus validate BUB1 as a novel molecular target." (PMID 39409911, 2024). "Our observation that BUB1 is upregulated across various lung cancer subtypes and its overexpression correlates with survival is consistent with earlier reports and reemphasizes its potential as a crucial molecular target in lung cancer." (PMID 39409911, 2024). "Our results demonstrate BUB1 inhibition as a promising strategy to sensitize lung cancers to radiation and chemoradiation therapies." (PMID 39409911, 2024). "Elevated levels of the mitotic checkpoint kinase BUB1 are frequently observed in most solid cancers, including lung cancer." (PMID 39409911, 2024). "BUB1 inhibitor BAY1816032 dose-dependently suppressed proliferation of lung cancer cells in the Alamar blue cytotoxicity assay." (PMID 39409911, 2024). "Confirmation of BUB1 protein overexpression in lung tumor TMAs and lung cancer cell lines further emphasizes its significance as a potential biomarker and a molecular target in lung cancer." (PMID 39409911, 2024). "These future studies will be critical for fully realizing BUB1’s potential as a therapeutic target in lung cancer." (PMID 39409911, 2024). "Budding uninhibited by benzimidazoles 1 (BUB1) is a mitotic checkpoint serine/threonine kinase, which promotes the proliferation of lung cancer cells." (PMID 35954210, 2022). "We analyzed lung cancer cohorts with KRAS mutations (GSE31210) and found that higher hub gene levels (BUB1, BUB1B, NCAPG, CDC20, CDK1, KIF11) were significantly associated with worse OS in lung cancer patients with KRAS mutations." (PMID 36176446, 2022). "In this study, we found that the expression of BUB1, CCNA2, CDC20 and KIF11 increased after inhibitor resistance compared with inhibitor-sensitive lung cancer samples, and these targets were associate with cell cycle, cell proliferation, DNA damage and EMT." (PMID 36176446, 2022). "Compared to primary lung cancer, all the expression of hub genes increased in lymph node metastasis samples, and the expression of BUB1, BUB1B, CDK1, CCNA2 and CDC20 were related to peritoneum metastasis." (PMID 36176446, 2022). "We discovered that many lncRNAs were located nearby important key regulators of lung cancer, including FN1, PCNA, BUB1, GNB1, and other cancer associated genes." (PMID 26918601, 2016). "In this study, we show a direct correlation between BUB1 protein expression and overall survival and establish BUB1 as a novel molecular target for enhancing the therapeutic potential of cisplatin, paclitaxel, olaparib, and ionizing radiation in lung cancer." (PMID 39409911, 2024). "However, the role of BUB1 in improving the effectiveness of radiotherapy or chemoradiation in lung cancers, and in particular SCLC, remains unexplored." (PMID 39409911, 2024). "These approaches will further strengthen the therapeutic targeting of BUB1 in lung cancer." (PMID 39409911, 2024). "In the present study, we aimed to evaluate if a BUB1 targeting agent could enhance the effectiveness of chemotherapy and chemoradiation in lung cancer." (PMID 39409911, 2024).
lung carcinoma (continued). "Hypothesis: We hypothesize that BUB1 (Ser/Thr kinase) is overexpressed in lung cancers and its inhibition will sensitize lung cancers to chemoradiation." (PMID 39409911, 2024). "As shown, several well‐known oncogenes were co‐expressed with circRNA, such as Wnt3A, CDK1, and BUB1, indicating these circRNA might participate in the pathological process of lung cancer." (PMID 29632808, 2018). "Low levels of Mad2 or Bub1 can induce lung cancer, which is confirmed by this study." (PMID 28915607, 2017). "Specifically, it was demonstrated that BUB1 inhibition regulates AKT phosphorylation to modulate mTOR and ERK signaling pathways in lung carcinoma and osteosarcoma, respectively." (PMID 40723917, 2025). "In the future, we anticipate a phase-1 clinical trial that evaluates the safety of BUB1 inhibitor BAY1816032 as a monotherapy and in combination with cisplatin, paclitaxel, PARP inhibitors, and radiotherapy in patients with lung cancer." (PMID 39409911, 2024). "Aurora B phosphorylates BUB1 to facilitate spindle assembly checkpoint signaling, and target Aurora B kinase can prevent and overcome resistance to EGFR inhibitors in lung cancer." (PMID 36176446, 2022). "In addition, the expression level of main hub genes (BUB1, CCNA2, CDC20, KIF11) was significantly higher in patients with EGFR TKI-resistant lung cancer tissues (GSE161584) than EGFR TKI-sensitive lung cancer tissues." (PMID 36176446, 2022). "Thereafter, we measured expression of five genes commonly considered as proliferative markers, Ki67, TOPO IIa, BUB1, CENP2, FOXM1, including in lung cancers; in the 10 NF-YA cohorts, all showed progressively decreasing levels from high-to-low NF-YA expressing tumors." (PMID 31744190, 2019).
pancreatic ductal adenocarcinoma (13 papers, 2020 to 2025). An infiltrating adenocarcinoma that arises from the epithelial cells of the pancreas. "Overexpression of BUB1 and BUB1B in tumor tissues is related to a poor prognosis in pancreatic ductal adenocarcinoma, and it is also associated with advanced tumor stage and tumor development." (PMID 35493295, 2022). "The cell cycle-related proteins CDK1 and BUB1 are significantly overexpressed in pancreatic ductal adenocarcinoma tissues and may be prognostic biomarkers." (PMID 35515103, 2022). "BUB1 mitotic checkpoint serine/threonine kinase (BUB1) is overexpressed in pancreatic ductal adenocarcinoma, which could be a useful parameter to predict the poor prognosis of pancreatic ductal adenocarcinoma (PDAC)." (PMID 34298705, 2021).